E2F3 (E2F transcription factor 3)
Diseases named in the same sentence as E2F3 in open-access papers (continued):
Sharing a sentence is not in itself a finding about the gene and the disease.
lung carcinoma (32 papers, 2010 to 2025). "E2F3 mRNA was highly expressed in lung cancer tissues and associated with poor survival outcomes for the patient, as well as promoted cell proliferation, migration, and invasion." (PMID 35635595, 2022). "E2F1 and E2F3 have been shown to be overexpressed and exert tumor-promoting effects in several types of cancers including lung cancer 10, 17, 43-45." (PMID 35844795, 2022). "Among these targets, E2F3 has a predicted targeting binding site of miR-138-5p, which was upregulated in lung cancer." (PMID 35635595, 2022). "Amplification or elevated expression of the E2F3 locus at 6p22.3 has been identified in breast, prostate, bladder, and lung cancers." (PMID 32429447, 2020). "As an important member of the E2F family, E2F3 affects tumorigenesis and progression in lung cancer and osteosarcoma." (PMID 33680929, 2020). "It has been verified that the overexpression of E2F3 transcription factor promotes the development of lung cancer." (PMID 30967126, 2019). "It has been reported that CITED2 promotes MYC-mediated transactivation of the E2F3 gene by recruiting p300 to stimulate lung cancer progression." (PMID 30291252, 2018). "According to a recent report, it was found that long non-coding RNA-NEAT1 promoted lung cancer cell growth in vivo by inhibiting miR-377-3p/E2F3 axis." (PMID 28947999, 2017). "Previous publications reported that E2F3 was amplified or over-expressed in several tumors, including bladder, prostate, kidney, and lung cancer." (PMID 28740578, 2017). "Transcriptomic alterations that occur during lung cancer development include over-expressed cell cycle related genes like E2F3, BUB3, CDK4, MCM2, MCM3, and MCM7 as summarized by Powell and Borczuk." (PMID 26930711, 2016). "FLVCR1-AS1 could conduce to lung cancer cell growth through sponging miR-573 to regulate E2F3 expression." (PMID 35101035, 2022). "The second suggests a cooperative function between RUNX2 and three transcription factors (BRCA1, FOXM1, and RUNX1) important for the specific regulation of lung cancer establishment and progression, along with three transcription factors (E2F3, FHL2, and TWIST1) of the NSCLC-GRN." (PMID 36551878, 2022). "In lung cancer, miR-138-5p inhibition could promote carcinogenesis and progression by targeting E2F3, CDK8, ZEB2, PD-L1, and PD-1, and the present results displayed that miR-138-5p is downregulated in LUSC tissues and cells." (PMID 35635595, 2022). "Suppression of E2F3 was shown to synergize the cytotoxicity of paclitaxel in lung cancer cells." (PMID 33924966, 2021). "Especially, E2F3 was confirmed that the expression increased significantly in lung cancer tissues." (PMID 32294625, 2020). "Moreover, E2F3, a downstream signaling molecule of CSF-1, has been found to increase expression of E2F3 in prostate cancer, ovarian cancer, and lung cancer, and the expression of E2F3 in TAMs can promote lung metastasis of tumors." (PMID 33224886, 2020). "In the lung carcinoma cell line (E114), DeepHistone recovered E2F3, TFAP2C and GRHL2." (PMID 30967126, 2019). "In lung cancer cells, miR-200b can target E2F3 to lessen cell sensitivity to docetaxel." (PMID 31419939, 2019). "For example, it has been reported that NEAT1 can promote lung cancer progression through the miR-377-3p–E2F3 axis, regulate EMT through the miR-204/ZEB1 pathway in nasopharyngeal carcinoma, and serves as a downstream target of ERα to play a critical role in carcinogenesis of prostate cancer." (PMID 29515109, 2018). "Also, downregulation of miR-449a was observed to be highly associated with tumor recurrence and lung cancer patients' survival, suggesting that miR-449a/E2F3 played a critical role in development of lung cancer." (PMID 28947999, 2017).
lung carcinoma (continued). "Meanwhile, enforced miR-449a could lead to cell cycle arrest and cell senescence via regulation of E2F3 expression in lung cancer cells." (PMID 28947999, 2017). "Furthermore, increased expression of miR-34a induced cell proliferation inhibition, cell cycle arrest and cell senescence of lung cancer cells by targeting E2F1/E2F3." (PMID 28389657, 2017). "Recent studies validated E2F3 as the direct target of various miRNAs, such miR-449a and miR-200b, to be involved in the abnormal proliferation and chemoresistance lung cancer, supporting its multifacet roles in the pathological onset or progression in lung cancer." (PMID 26942465, 2016). "LncRNA FLVCR1-AS1 could sponge miR-573 to upregulate E2F3 in lung cancer." (PMID 32669972, 2020). "FOXM1 is overregulated in nine lung cancer datasets and is related to: 1) the negative regulation of transcription along with E2F1, FOXE1, and HMGA1; 2) cellular senescence along with E2F1, E2F3, and MYBL2; and 3) DNA repair and damage." (PMID 39228892, 2024). "Different from E2F3 and TFAP2C, GRHL2 can suppress tumor metastasis by regulating of transcriptional activity of RhoG in lung cancer." (PMID 30967126, 2019). "E2F1 is overregulated in seven lung cancer datasets and is related to: 1) HPV infection; 2) HBV and EBV virus infection along with E2F3; 3) the cell cycle and pathways in cancer along with E2F3; and 4) HTVL-I infection along with E2F3 and TCF3." (PMID 39228892, 2024). "According to the TRN of lung cancer, SOX4, FOXM1, ETV4, HOXC6, and E2F3 are the main positive regulators, whereas SOX17, KLF4, and ZBTB16 are the main negative regulators of transcription, controlling the expression of other TFs and target genes in lung cancer." (PMID 39228892, 2024). "Similarly, RUNX2 is a coregulator of three TFs (E2F3, FHL2, and TWIST1) that also appear in the NSCLC lung cancer regulatory network." (PMID 36551878, 2022). "While E2F3 expression in TAMR-1 cells was not previously determined, previous studies reported that E2F3 expression was elevated in paclitaxel-resistant MCF-7 cells, as well as different resistant cancer types, including ovarian and lung cancer cells." (PMID 38864530, 2024). "Moreover, RUNX2 is a coregulator of three of the transcriptional regulators identified in the NSCLC-GRN (i.e., E2F3, FHL2, and TWIST1), suggesting a cooperative function of these TFs in lung cancer, which has not been studied experimentally in lung cancer." (PMID 36551878, 2022). "Interestingly, in the present study, we identified that E2F2, E2F3, and E2F4 were not essential genes in lung cancer cells from Project Achilles." (PMID 33924966, 2021).
gastric cancer (29 papers, 2015 to 2025). A primary or metastatic malignant neoplasm involving the stomach. "Protein-level validation using immunohistochemistry (IHC) data from the HPA database revealed that THBS2, CTNNB1, COL4A1, and E2F3 exhibited markedly higher staining intensity in gastric cancer tissues compared to normal gastric mucosa." (PMID 41291892, 2025). "Our analysis identified hsa-miR-9-3p and hsa-miR-9-5p as shared regulators of COL4A1, CTNNB1, THBS2, and E2F3, a pattern that aligns partially with earlier studies reporting dysregulation of the miR-9 family in gastric cancer." (PMID 41291892, 2025). "It is also stated that the E2F3 expression at the protein and mRNA level was significantly downregulated in gastric cancer cells after miR-141 transfection." (PMID 39116089, 2024). "Of note, m6A modification on the E2F transcription factor 3 (E2F3) mRNA was required for the interaction between miR-660 and E2F3 mRNA in gastric cancer, indicating that m6A also affects the function of miRNA apart from participating in its production process." (PMID 36614216, 2023). "In the study of glioma, SNHG5 promotes tumor growth by targeting E2F3, and E2F3 and E2F1 are both transcription factors of the E2Fs encoding gene family and are associated with poor prognosis of gastric cancer." (PMID 37258567, 2023). "Circ_PGPEP1 promotes gastric cancer proliferation, invasion and migration by regulating E2F3 levels." (PMID 34741389, 2021). "The expression of E2F3, miR-17-92a-1 cluster host gene (MIR17HG), and miR-17-92 cluster miRNAs was significantly reduced in EBV-associated gastric carcinoma (EBVaGC) patients compared with EBV-negative gastric carcinoma (EBVnGC) patients." (PMID 34681596, 2021). "E2F3 is highly expressed in gastric carcinoma tissues and regulates DKK3 expression by modulating miR-125a expression, ultimately promoting gastric cancer cell proliferation, migration, and invasion." (PMID 34657558, 2021). "For example, miR-203a can suppress cell proliferation through targeting E2F3 in human gastric cancer." (PMID 31737898, 2019). "Expression of miR-141 and MEG3 can abolish the expression of E2F3 and inhibit the process of gastric cancer." (PMID 30429233, 2018). "MiRNA targeting (miR-577) of E2F3 was found to inhibit gastric cancer cell progression, and miRNA targeting of E2F3 and CCND1 (miR-449b) was found to inhibit the proliferation of SW1116 colon cancer stem cells." (PMID 28589857, 2017). "For example, miR-564 regulates the expression of TGF-β1 to suppress glioma cell proliferation and invasion, and miR-564 plays a role in the regulation of E2F3 in gastric cancer." (PMID 29296185, 2017). "In gastric cancer cells, significant G0/G1 arrest was also observed after transfection of miR-449a mimics, which were stimulated by directly targeting of E2F3." (PMID 28947999, 2017). "In gastric cancer cells, miR-145 mediated the anti-proliferative effects of vitamin D3 by directly targeting E2F3." (PMID 28947999, 2017). "It was also reported that miR-449a and miR-145 played tumor suppressive roles by targeting E2F3 in gastric cancer." (PMID 28947999, 2017). "Overexpression of miR-145 was also found to inhibit gastric cancer cell proliferation through regulation of E2F3-dependent cell cycle transition." (PMID 28947999, 2017). "A novel study suggested that 1,25(OH)2D3 inhibited proliferation of gastric cancer cells via regulation of miR-145 and its target E2F3 and targeting vitamin D/miR-145/E2F3 pathway will be a potential strategy for gastric cancer treatment." (PMID 28947999, 2017). "miR-449a was downregulated in gastric cancer cell lines and gastric cancer tissues, and inhibits proliferation and induces apoptosis by directly repressing E2F3." (PMID 26576674, 2015). "miR-203a targeted E2F3 in gastric cancer to inhibit proliferation and colony formation." (PMID 33680969, 2021).
gastric cancer (continued). "Another study on gastric cancer suggested that miR-141 could play an important anti-tumor role by interacting with MEG3 and targeting E2F3 during gastric cancer pathogenesis and may be a therapeutic target." (PMID 31827401, 2019). "Also, re-expression of miR-449a significantly increased apoptosis of gastric cancer cells by targeting E2F3." (PMID 28947999, 2017). "However, EBV-miR-BART1-3p could induce G0/G1 arrest and inhibit cell growth in gastric carcinoma cells by targeting E2F3 mRNA and regulating miR-17-92 cluster, and has even been detected in exosome of EBVaGC." (PMID 40855561, 2025). "Currently, the regulatory role of E2F3 in the senescence process is unclear, but its m6A modification is involved in miRNA/E2F3-mediated proliferation inhibition of gastric cancer cells, thus suggesting that m6A modification in E2F3 may also be an important factor of cell senescence." (PMID 36012545, 2022). "MiR-141 was reported to inhibit gastric cancer proliferation by interacting with MEG3 and suppressing E2F3 expression." (PMID 33981611, 2021). "In gastric cancer, lncRNA SBF2-AS1 plays oncogenic roles via regulating the miR-302b-3p-E2F Transcription Factor 3 (E2F3) axis." (PMID 32976115, 2020). "LincRNA CRNDE was highly expressed in gastric cancer cells, and overexpression of CRNDE increased cell viability and promoted colony formation via sponging miR-145 and activation of its target gene E2F3." (PMID 28832500, 2017). "E2F3 staining was strongly positive in gastric cancer sample sections but was weak or absent in normal tissues." (PMID 41291892, 2025).
hepatocellular carcinoma (29 papers, 2013 to 2025). A malignant tumor that arises from hepatocytes. "Ultimately, overexpression of E2F3, which is an oncogene in tumorigenesis, is associated with a poor prognosis in a variety of human malignancies, such as hepatocellular carcinoma." (PMID 31423109, 2019). "Overexpression of miR-34a and miR-214 was also found to inhibit the proliferation of hepatoma cells by downregulating the expression of E2F3." (PMID 36175803, 2022). "Through the repression of E2F3, miR-144 represses hepatocellular carcinoma (HCC) cell proliferation." (PMID 33046994, 2020). "For instance, miR-195 can bind the 3′UTRs of cyclin D1, CDK6, and E2F3, thereby suppressing cell proliferation in human hepatocellular carcinoma cells." (PMID 29426937, 2018). "Previous studies have shown that miRNA-424-5p suppresses the expression of SOCS6 in pancreatic cancer and inhibits the Akt3/E2F3 axis and tumour growth in hepatocellular carcinoma." (PMID 29716627, 2018). "Decreased expression of miR-217 was found to be significantly associated with large tumor size and advanced clinical stage, and miR-217 directly suppressed E2F3 and thereby inhibited invasion of hepatocellular carcinoma." (PMID 28589857, 2017). "PPIX, regulating miR-199a-5p/E2F3, prevented tumor cell growth and migration of tumor cells and sensitized mesenchymal hepatoma cells to chemotherapeutic agents." (PMID 28947999, 2017). "MiR-217 inhibits clear cell renal cell carcinoma, hepatocellular carcinoma, gastric cancer and glioma by targeting E2F3, EZH2 and Runx2, respectively." (PMID 28437471, 2017). "Recent data suggests that miR-217 is an oncogene that is overexpressed in aggressive human B cell lymphomas and contradictarorily functions as a potential tumor suppressor in hepatocellular carcinoma through direct suppression of E2F3." (PMID 25807141, 2015). "For example, miR-214 can inhibit the activity of hepatocellular carcinoma by targeting E2F3." (PMID 35692501, 2022). "Moreover, miR-507 participates in the hsa_circ_0005394/miR-507/E2F3 axis and affects the process of hepatocellular carcinoma." (PMID 32908877, 2020). "Furthermore, miR-217 was reported to inhibit invasion of hepatocellular carcinoma cells through targeting E2F3." (PMID 28437471, 2017). "CHEK1, CDC25A, and CCNE1, together with CCND1, CCND3, CDK4, CDK6, BTRC, E2F3, and FOXK1, were previously identified as the targets of miR‐497∼195 cluster in hepatocellular carcinoma." (PMID 40548926, 2025). "In the hepatocellular carcinoma cells, SNHG15 served as the competitive endogenous RNA, increased the expression of E-box Binding Homeobox 2 (EZB2) and E2F Transcription Factor 3 (E2F3) via sponging miR-141-3p and mediating the cell proliferation, G0/G1 arrest and cell invasion." (PMID 32633324, 2020).
prostate carcinoma (27 papers, 2009 to 2025). A carcinoma that arises from epithelial cells of the prostate gland. "Further studies are needed to determine the potential role of the E2F3 cistrome in mediating RB1 loss–driving prostate cancer progression and therapeutic vulnerabilities." (PMID 36928314, 2023). "E2F3 is associated with various other processes and plays an important role in the progression of a variety of cancers, such as bladder, breast, and prostate cancers." (PMID 35565529, 2022). "For instance, to predict overall survival and cause-specific survival in prostate cancer, E2F3 is considered a relatively independent factor." (PMID 31419939, 2019). "In prostate cancer E2F3 overexpression is linked to tumour aggressiveness." (PMID 39337607, 2024). "For prostate cancer, E2F3 may be an independent factor predicting overall and cause-specific survival." (PMID 28903320, 2017). "E2F3 is a potent transcriptional inducer of cell-cycle progression and its amplification was strongly associated with invasive tumor phenotype and high tumor grade in a subset of bladder tumors and in prostate cancer." (PMID 25889255, 2015). "E2F3 was generally considered to increase cellular proliferation as a transcriptional activator through promoting the G1/S transition and its amplification was strongly associated with invasive tumor phenotype and high tumor grade in a subset of bladder tumors and prostate cancer." (PMID 26942465, 2016). "E2F3 levels have a critical role in modifying cellular proliferation rates in human prostate cancer by removing retinoblastoma protein (pRB) suppressor control at the G1/S transition in the cell cycle." (PMID 39337607, 2024). "Through the establishment of a prostate cancer nude mouse model, we discovered that lncRNA H19 bolstered tumor growth, augmented positive Ki67 cells, and enhanced E2F3 expression, whereas Brevilin A dampened the promoting effect of lncRNA H19." (PMID 37253635, 2023). "To conclude, Brevilin A modulates the biological behaviors of prostate cancer cells via the lncRNA H19/miR-194/E2F3 axis." (PMID 37253635, 2023). "In conclusion, our study has confirmed that Brevilin A impedes prostate cancer cell proliferation, migration, and invasion and exerts its anti-tumor function in prostate cancer through modulating the lncRNA H19/miR-194/E2F3 signaling pathway." (PMID 37253635, 2023). "To figure out the impact of miR-194 and E2F3 on prostate cancer cells, we transfected E2F3 overexpression plasmids or E2F3 siRNA after miR-194 mimics or inhibitors were added." (PMID 37253635, 2023). "qRT-PCR suggested that lncRNA H19 and E2F3 expressions were obviously elevated in prostate cancer tissues versus adjacent normal tissues, while miR-194 expression was substantially lowered." (PMID 37253635, 2023). "Our findings exhibited that miR-194 played its part as an oncogene in prostate cancer, but E2F3 inverted the anti-tumor function of miR-194." (PMID 37253635, 2023). "Here, E2F3 mRNA and protein expressions exhibited a considerable increase in prostate cancer cells and tissues, indicating that the abnormal profile of E2F3 had a potential correlation with prostate cancer." (PMID 37253635, 2023). "Our study probed the functions of Brevilin A in prostate cancer cells and the mechanisms among Brevilin A, lncRNA H19, miR-194, and E2F3 on the biological behaviors of the cells." (PMID 37253635, 2023). "It is reported that the functions and transcriptional activity of E2F3 are altered in a variety of human malignancies, including lung, ovarian, bladder, gastric, and prostate cancers." (PMID 36457717, 2022). "The findings suggest that VA acts as a HDAC3 inhibitor with anti-cancer effect on prostate cancer by regulating E2F1/E2F3/CASP3 axis." (PMID 36175803, 2022). "Consistent with our study, E2F3 was found to be over-expressed in PCa and to stimulate the proliferation of prostate cancer cells." (PMID 35531101, 2022).